KIF1B (kinesin family member 1B)
Diseases named in the same sentence as KIF1B in open-access papers (continued):
Sharing a sentence is not in itself a finding about the gene and the disease.
KIF1B also shares sentences with these, for which no sentence is quoted: chronic hepatitis B (3 papers); Charcot-Marie Tooth Disease type 2A1 (2); neurodevelopmental disorder (2); Obesity (2); adrenocortical adenoma (1); alcohol dependence (1); alcohol liver disease (1); autism (1); autoimmune disease (1); autosomal dominant inherited disorders (1); Budd–Chiari syndrome (1); cognitive disorder (1); colon cancer (1); COVID-19 (1); diabetes (1); digestive system disorder (1); ganglioneuroma (1); gastric cancer (1); head and neck paraganglioma (1); heart failure (1); hemorrhagic stroke (1); hepatitis B virus infection (1); hereditary spastic paraplegia (1); ischemic stroke (1); kidney disease (1); leiomyosarcoma (1); liver cirrhosis (1); liver diseases (1); lung adenocarcinoma (1); lung carcinoma (1).
A further 13 diseases each share a sentence with KIF1B in 1 paper.